LGALS3 (galectin 3)
Diseases named in the same sentence as LGALS3 in open-access papers (continued):
Sharing a sentence is not in itself a finding about the gene and the disease.
benign thyroid tumors (6 papers, 2012 to 2021). "In comparison with other established biomarkers for PTC, the expression rate of hsa-miR-200a-5p was higher than that of Galectin-3 and MC, and therefore can be in differential diagnosis between PTC and benign thyroid tumors." (PMID 30005075, 2018). "At present, there are some markers for the differential diagnosis of PTC and benign thyroid tumor with papillary hyperplasia, such as CK19/Galectin-3/HBME1, but they are limited in clinical use because of their relative lower sensitivity and specificity." (PMID 30005075, 2018). "Although Galectin-3 and MC are frequently expressed in PTC, and TPO and CD56 are frequently expressed in benign thyroid tumor, the sensitivity of these markers remains unsatisfactory." (PMID 30005075, 2018). "The has-miR-200a-5p as an overexpressed molecule is a sensitive biomarker and could be combined with immunohistochemical markers such as TPO, CD56, Galectin 3, MC, CK19, and BRAF both to detect and to distinguish between PTC and benign thyroid tumor with papillary hyperplasia." (PMID 35186709, 2021).
cerebral malaria (6 papers, 2009 to 2025). A sequestration of Plasmodium falciparum in the brain, which can cause coma and/or seizures. "With respect to malaria, galectin-3 was postulated to promote cerebral malaria in experimental settings as galectin-3 deficient mice was protected." (PMID 40802820, 2025).
cerebrovascular diseases (6 papers, 2020 to 2026). "Research has consistently highlighted galectin-3 (Gal-3) as a leading biomarker candidate for cardiovascular and cerebrovascular disease." (PMID 41988369, 2026).
cholangiocarcinoma (6 papers, 2015 to 2022). A carcinoma that arises from the intrahepatic biliary tree (intrahepatic cholangiocarcinoma) or from the junction, or adjacent to the junction, of the right and left hepatic ducts (hilar cholangiocarcinoma). "The expression pattern obtained here, with CYP3A5 down-regulation expression gene (cytochrome P450 family) and LGALS3 up-regulation expression gene (galectine 3), could also be used to explain the lack of association between infection with F. hepatica and cholangiocarcinoma." (PMID 26247779, 2015). "On the other hand, the sensitivity of cholangiocarcinoma cells to cisplatin- and 5-FU-induced apoptosis was increased only when galectin-3 expression was almost completely diminished by siRNA (< 10%), whereas the reduction of galectin-3 expression only to 50% did not induce apoptosis." (PMID 30585294, 2019).
co-infection (6 papers, 2016 to 2024). "Galectin-3 has been implicated in modulating the immune response during IAV and S. pneumoniae co-infection." (PMID 37298569, 2023). "We now show experimentally that galectin-3 levels were further synergistically suppressed in TV co-infection with P. bivia, which provides a mechanism for clinically reduced cervicovaginal galectin-3 levels in TV–BV co-infected women compared to TV alone observed in our study." (PMID 34422675, 2021). "Galectin-3 modulates SOCS1 expression, which may contribute to the overall inflammatory response, and can influence RIG-I expression during co-infection, leading to dysregulated expression and release of pro-inflammatory cytokines." (PMID 37298569, 2023).
colon adenocarcinoma (6 papers, 2013 to 2022). "P-(GFLG-DOX)-TriGal contains trivalent galactose, which can also be biorecognized by galectin-3 on the surface of colon adenocarcinoma cells." (PMID 23291656, 2013). "In this study, we examined the effects and mechanisms of silencing galectin-3 via RNA interference (RNAi) on the β-catenin/GSK-3β pathway in human colon adenocarcinoma Caco-2 cells." (PMID 24303084, 2013). "Moreover, α2-6 sialylation of β1 integrins is increased in colon adenocarcinoma tissues and blocks its adhesion to galectin-3, thus protecting the cells against galectin-3-induced apoptosis in SW48 CRC cells." (PMID 26539643, 2016). "P-(GFLG)-DOX-GalN (25,000 g/mol), contains N-acylated galactosamine (GalN), which was designed to be recognized by ASGPR in HepG2 human hepatocellular carcinoma cells and individual members of the galectin family (e.g., galectin-3) in human colon adenocarcinoma." (PMID 23291656, 2013). "The expression of upstream survival signals (GSK-3β, β-catenin, c-myc and cyclin D1) in human colon adenocarcinoma Caco-2 cells was evaluated after epirubicin treatment with or without galectin-3 knockdown." (PMID 24303084, 2013).
coronary atherosclerosis (6 papers, 2017 to 2025). Atherosclerosis of the coronary vasculature. "Recent studies have highlighted the roles of galectin-3 and pentraxin-3 as potential biomarkers in coronary atherosclerosis, yet their specific interactions and implications in patients with CCS and AF remain underexplored." (PMID 40430046, 2025). "Galectin-3 was associated with OSA severity, but also with coronary atherosclerosis estimated by coronary CT angiography." (PMID 39941305, 2025).
ischemic cardiomyopathy (6 papers, 2015 to 2024). Ischemic cardiomyopathy is a cardiomyopathy in which a weakness in the muscle of the heart due to inadequate oxygen delivery to the myocardium with coronary artery disease being the most common cause. "Cardiac magnetic resonance and galectin-3 level as predictors of prognostic outcomes for non-ischemic cardiomyopathy patients." (PMID 34550239, 2021). "It has been shown that Galectin-3 measured after STEMI is an independent predictor of increased ECV at 6 months; it is also associated with myocardial replacement fibrosis assessed by LGE in patients with non-ischemic cardiomyopathy." (PMID 37297827, 2023).
juvenile idiopathic arthritis (6 papers, 2018 to 2023). Juvenile idiopathic arthritis (JIA) is the term used to describe a group of inflammatory articular disorders of unknown cause that begin before the age of 16 and last over 6 weeks. "Previous studies documented the changed levels of galectin-3 in patients with RA, juvenile idiopathic arthritis (JIA), SSc, ankylosing spondylitis (AS), or Behcet’s diseases (BD)." (PMID 33076422, 2020). "Galectin-1 expression is downregulated and galectin-3 expression is upregulated in synovial tissue from patients with juvenile idiopathic arthritis." (PMID 30525048, 2018). "The identification of increased galectin-3 in RA and juvenile idiopathic arthritis has led authors to hypothesize that galectin-3 precipitates inflammatory arthritis." (PMID 30525048, 2018).
Left ventricular diastolic dysfunction (6 papers, 2021 to 2024). Abnormal function of the left ventricule during left ventricular relaxation and filling. "Limited data are also available for the pediatric population, with a study of 67 children on maintenance hemodialysis showing that serum galectin-3 is associated with left ventricular diastolic dysfunction." (PMID 38519721, 2024). "Additionally, serum galectin-3 levels were found to be significantly higher in hemodialysis patients with left ventricular diastolic dysfunction, presenting a positive correlation with E/E ́ ratio (r: 0.645, p-value < 0.001)." (PMID 38519721, 2024).
malaria (6 papers, 2009 to 2025). Malaria is a serious and sometimes fatal disease caused by a parasite that commonly infects a certain type of mosquito which feeds on humans. "Further studies are needed to properly define the exact role of galectin-3 in the evolution of T2DM in malaria-endemic regions of the globe." (PMID 40802820, 2025). "In as much as these results give further credence to the probable diabetogenic role of galectin-3 in our sample, irrespective of disease background, they point to different mechanisms by which malaria associates with the different groups of respondents." (PMID 40802820, 2025). "Therefore, we measured the capacity of galectin-3 to adhere to malaria parasites after incubation of mouse recombinant galectin-3 with Pb-A schizonts for 1 h at 37°C." (PMID 19710907, 2009). "A similar type of mechanism related to the processing of galectin-3 that is triggered by only a few Plasmodium species might be a reason why not all malaria parasites cause the pathogenesis of CM in their respective hosts." (PMID 19710907, 2009). "Serum galectin-3 level was generally higher in participants with malaria and lowest in non-diabetic participants without malaria." (PMID 40802820, 2025). "A positive correlation (r = 0.316; P < 0.05) between BMI and galectin-3 was observed only in the non-diabetic patients with malaria." (PMID 40802820, 2025). "In diabetic patients who had malaria, a negative correlation was found between galectin-3 and HOMA-B." (PMID 40802820, 2025). "Thus, it appears that in malaria, increased galectin-3 increased HOMA-B in the non-diabetic respondents but reduced it in the diabetic respondents." (PMID 40802820, 2025). "This positive correlational trend was observed between galectin-3 and insulin as well as HOMA-B in the non-diabetic respondents with malaria." (PMID 40802820, 2025).
myocardial ischemia (6 papers, 2022 to 2025). A disorder of cardiac function caused by insufficient blood flow to the muscle tissue of the heart. "These events mediate the involvement of Ang-2 and MMP-9 in vascular injury during ICMP, which is associated with an excessive galectin-3 production in the myocardium and forms a vicious circle of myocardial ischemia." (PMID 37509589, 2023). "Furthermore, the prognostic value of serum galectin-3 in children with sickle cell diseases was assessed in two studies suggesting that galectin-3 can be indicative of myocardial ischemia during vaso-occlusive crisis and a susceptibility factor for vaso-occlusive crisis frequency." (PMID 35410028, 2022).
pancreatic adenocarcinoma (6 papers, 2019 to 2025). "Galectin-3 (Gal-3) plays a multifaceted role in the development and progression of pancreatic adenocarcinoma (PAAD), which is associated with a poor prognosis." (PMID 40600063, 2025). "Transcript levels of LGALS3 were significantly higher in pancreatic adenocarcinoma samples as compared to normal pancreas sample, although a fraction of samples showed overlapping LGALS3 levels with the normal tissue counterpart." (PMID 41153387, 2025). "In the same way, galectin-3 inhibition in a pancreatic adenocarcinoma allogeneic vaccine increased disease-free survival in patients." (PMID 34572756, 2021). "Galectin-3 has been involved as a major determinant of cold tumors (those which do not respond to immune checkpoint inhibitors due to the paucity of tumor T cell infiltration, as happens in prostate and pancreas adenocarcinomas); galectin-3 inhibition can reverse such resistance." (PMID 34572756, 2021). "Another study focused on the diagnostic value of galectin-3 in inflammatory pancreatic disease and indicated that galectin-3 is not an interesting biomarker for the detection of pancreatic adenocarcinoma." (PMID 31832021, 2019). "In a subset of lung and pancreatic adenocarcinomas addicted to mutant KRAS, the disruption of galectin-3/β3 interaction by GCS-100, a galectin-3 antagonist currently under clinical development, released mutant KRAS from β3 and inhibited tumor growth in mice." (PMID 31109009, 2019).
parathyroid tumors (6 papers, 2010 to 2025). "For the patients with parathyroid neoplasms (PC, APT and PA), higher serum iPTH was associated with Ki-67 > 5% (P = 0.035), positive EZH2 (P < 0.001), galectin-3 (P = 0.002) and PGP9.5 staining (P = 0.027)." (PMID 38340242, 2024). "Cdc73+/−, Cdc73+/L/PTH-Cre and Cdc73L/L/PTH-Cre mice developed parathyroid tumours, which had nuclear pleomorphism, fibrous septation and increased galectin-3 expression, consistent with atypical parathyroid adenomas, from 9 months of age." (PMID 28288139, 2017). "Among 107 patients in this cohort, negative parafibromin expression in parathyroid neoplasms was significantly associated with overexpression of Ki-67, galectin-3, and PGP9.5, while E-cadherin staining loss was independent of other biomarkers." (PMID 38340242, 2024). "In addition, galectin-3 and human telomerase reverse transcriptase (hTERT) constitute two other markers of promising value which could be of clinical importance when assessing parathyroid tumours of uncertain malignant potential." (PMID 21197463, 2010).
pneumococcal infection (6 papers, 2016 to 2021). Infections with bacteria of the species streptococcus pneumoniae. "β2-integrin independent transmigration into alveoli during Streptococcus pneumoniae infection may also been mediated by galectin-3, a β-galactoside-binding protein released by alveolar resident macrophages, or pulmonary parenchyma cells." (PMID 28982143, 2017). "Therefore, our results suggest that children with SCA and low serum GAL-3 levels or carrying LGALS3 intermediate/low serum genotypes may have disvantages in the defense against pneumococcal infections reflected by the higher FRTI in the children with SCA." (PMID 27603703, 2016).
retinal disease (6 papers, 2015 to 2023). "We then investigated the effects of galectin-3 knockout on retinal disease progression using in vivo spectral domain optical coherence tomography (SD-OCT)." (PMID 36115971, 2022). "As galectin-3 may exert opposite effects on microglia and Müller glia in the context of a retinal disease process, therapies manipulating galectin-3 may need to consider cell type-specific targeting." (PMID 35711472, 2022).
schizophrenia (6 papers, 2018 to 2025). A major psychotic disorder characterized by abnormalities in the perception or expression of reality. "Galectin 3 level was significantly higher in bipolar disorder patients with psychotic symptoms compared to schizophrenia patients." (PMID 40638465, 2025). "LGALS3 encodes a member of the galectin family and may play a role in the pathogenesis of schizophrenia by participating in inflammatory processes in the central nervous system; high expression levels of LGALS3 have been detected in patients with schizophrenia." (PMID 37383091, 2023). "Galectin-3 serum levels in patients with schizophrenia were higher compared to healthy controls and positively correlated with the results obtained in the Brief Psychiatric Rating Scale." (PMID 32455781, 2020). "Although the significance of inflammation in the pathogenesis of schizophrenia is well documented, the role of Galectin-3 in this process remains unclear." (PMID 32455781, 2020). "An investigation regarding the interconnections between Galectin-3, IL-33 and soluble ST2 (sST2) in various stages of schizophrenia showed significant alterations of these markers of innate immunity in disease remission and exacerbation." (PMID 32455781, 2020).
chronic hepatitis (5 papers, 2018 to 2024). An active inflammatory process affecting the liver for more than six months. "Serum galectin-3 level was significantly higher in the patients with HCC compared to the healthy volunteers or the patients with chronic hepatitis (MD = 2.71, 95% CI = 1.56–3.85, p < 0.001) with a significant heterogeneity (I2 = 86.9%, p < 0.001)." (PMID 34778306, 2021). "On the other hand, IL-34 has been found overexpressed in chronic hepatitis, inducing pro-fibrotic macrophages to release transforming growth factor β, platelet-derived growth factor, as well as galectin-3." (PMID 30050466, 2018). "In another study, Galectin-3 levels were found to increase chronic hepatitis." (PMID 36225452, 2022).
chronic myelogenous leukemia (5 papers, 2012 to 2022). "We first tested GM-CT-01 on K562, a chronic myeloid leukemia cell line that constitutively produces both endogenous Galectin-3 and Galectin-1." (PMID 36430839, 2022). "In the case of LGALS1, a recent report characterized the induction of resistance to a variety of anticancer drugs following ectopic expression of galectin-3 in chronic myelogenous leukemia cells." (PMID 22848499, 2012).
coronary stenosis (5 papers, 2022 to 2025). Narrowing of the coronary artery lumen diameter. "Our findings suggest a strong association between galectin-3 levels and the severity of coronary stenosis." (PMID 40430046, 2025). "This proof-of-concept study aimed to explore the association between galectin-3, pentraxin-3, systemic inflammatory markers, the severity of coronary stenosis, and AF burden in a cohort of patients with CCS and/or AF." (PMID 40430046, 2025). "Our data support this distinction: galectin-3 was more prominently associated with the severity of coronary stenosis, whereas pentraxin-3 showed variable expression across AF subtypes, potentially reflecting dynamic endothelial or inflammatory activation rather than a fixed fibrotic state." (PMID 40430046, 2025). "Elevated levels of galectin-3 appear to correlate with coronary stenosis severity and may inform future strategies for risk stratification, patients’ selection for invasive coronarography or therapeutic targeting in CCS." (PMID 40430046, 2025).
cyst (5 papers, 2017 to 2024). A sac-like closed membranous structure that may be empty or contain fluid or amorphous material. "In addition, higher concentrations of galectin-3 were associated with lower eGFRcrea-cyst and eGFRcrea." (PMID 36175599, 2022). "We also detected high levels of Galectin-3 in HGSC cyst fluid, which is the fluid found surrounding the primary tumor in the ovary." (PMID 39759523, 2024). "Plasma galectin-3 concentrations were negatively correlated with eGFRcrea-cyst in patients with normoalbuminuria and albuminuria (γ = − 0.405, P < 0.001; γ = − 0.525, P < 0.001, respectively)." (PMID 36175599, 2022). "Galectin-3 concentration was measured in ascites, cyst fluid and serum or plasma." (PMID 39759523, 2024). "High levels of Galectin-3 were observed in cyst fluid and ascites from patients with HGSC." (PMID 39759523, 2024). "Also, ovarian cyst fluid collected from the primary tumor site contained increased levels of Galectin-3 as compared to paired serum (median 92.1 ng/ml in cyst fluid)." (PMID 39759523, 2024). "Greater concentrations of plasma galectin-3 were associated with lower eGFRcrea-cyst and eGFRcrea levels in patients with and without albuminuria." (PMID 36175599, 2022). "Negative correlations were observed between plasma galectin-3 and eGFRcrea-cyst in patients with normoalbuminuria (γ = − 0.405, P < 0.001) and albuminuria (γ = − 0.525, P < 0.001)." (PMID 36175599, 2022). "However, we observed that following Nx, the lack of Galectin-3 (Nx gal3−/−) leads to increased kidney weight increase and severe tubular alterations, specifically cyst development, unlike their cyst-free wt littermates." (PMID 28469279, 2017).
memory impairment (5 papers, 2017 to 2024). "Identification of proteins that interact with galectin-3 in neurons and elucidation of the molecular mechanism underlying galectin-3 phosphorylation-mediated memory impairment will require further investigation." (PMID 28744198, 2017).
Mitral regurgitation (5 papers, 2015 to 2022). An abnormality of the mitral valve characterized by insufficiency or incompetence of the mitral valve resulting in retrograde leaking of blood through the mitral valve upon ventricular contraction. "Galectin-3 levels showed significant correlation with GLS, with the grade of LV diastolic dysfunction, with septal E/e’, and with the grade of mitral regurgitation, even in age adjusted analysis." (PMID 35042522, 2022). "Similar results were revealed previously that dogs with MMVD showed increased galectin-3 concentration without significant differences according to the ACVIM classification or severity of mitral regurgitation." (PMID 34722704, 2021).